ZNF214 (zinc finger protein 214)
Description:
May be involved in transcriptional regulation.
Synonyms: BAZ-1; BAZ1
Tractability: PROTAC: ubiquitination databases record sites on it.
Gene: Protein-coding gene on chromosome 11 (6,996,671 to 7,020,355, reverse strand). Ensembl gene ENSG00000149050.
Subcellular location: Nucleus
Subcellular location (Human Protein Atlas): Nucleoplasm; Midbody
Pathways (Reactome):
Gene expression (Transcription): Generic Transcription Pathway
Gene Ontology:
Molecular function: DNA-binding transcription factor activity; zinc ion binding
Biological process: regulation of DNA-templated transcription
Cellular component: nucleoplasm; nucleus
Genetic constraint (gnomAD): Loss-of-function variants: 45 observed, 56.83 expected, observed/expected ratio (o/e) 0.79, 90% interval 0.62 to 1.01. The upper end of that interval is the gene's LOEUF score, 1.01, which puts it in group 4 of 6, group 1 being the genes least tolerant of losing a copy. Missense variants: 716 observed, 748.9 expected, observed/expected ratio (o/e) 0.96, 90% interval 0.9 to 1.02. Synonymous variants: 214 observed, 238.35 expected, observed/expected ratio (o/e) 0.9, 90% interval 0.8 to 1.01.
Homologues: Orthologues: chimpanzee ZNF214 (99% identical), macaque ZNF214 (95% identical), dog ZNF214 (84% identical), rabbit ZNF214 (79% identical). Paralogues in human: ZNF285 (40% identical), ZNF287 (39% identical), ZNF527 (38% identical), ZNF233 (36% identical), ZKSCAN7 (36% identical), ZNF852 (36% identical), ZNF34 (35% identical), ZNF572 (35% identical), ZNF17 (33% identical), ZNF222 (33% identical), ZNF530 (33% identical), ZNF155 (32% identical), and 38 more.
Diseases named in the same sentence as ZNF214 in open-access papers:
ZNF214 is named in the same sentence as 6 diseases in open-access papers, as found by Europe PMC text mining. Sharing a sentence is not in itself a finding about the gene and the disease. The quoted sentences say what the papers report.
tumours (1 paper, 2015). "Another gene located closely to significant marker rs134495844 is coding zing finger protein 214 (ZNF214) - a potential tumour suppressor gene whose expression is increased in tumours derived from testicular germ cells." (PMID 25585689, 2015).
ZNF214 also shares sentences with these, for which no sentence is quoted: Beckwith-Wiedemann syndrome (1 paper); Intellectual disability (1); male infertility (1); Obesity (1); pituitary hormone deficiency (1).